SNORA74A (small nucleolar RNA, H/ACA box 74A)
Synonyms: U19; RNU19
Gene: Small nucleolar RNA gene on chromosome 5 (139,278,781 to 139,278,978, forward strand). Ensembl gene ENSG00000200959.
Gene Ontology:
Biological process: RNA processing
Cellular component: nucleolus
Homologues: Orthologues: chimpanzee SNORA74 (100% identical), macaque SNORA74 (98% identical), dog SNORA74 (90% identical), pig SNORA74 (88% identical), rabbit SNORA74A (87% identical), rat Snora74a (87% identical), mouse Snora74a (86% identical), guinea pig SNORA74A (81% identical). Paralogues in human: SNORA74 (85% identical), SNORA74B (61% identical), SNORA74C-2 (60% identical), SNORA74C-1 (59% identical), SNORA74 (47% identical), SNORA74 (36% identical), SNORA74D (36% identical).
Diseases named in the same sentence as SNORA74A in open-access papers:
SNORA74A is named in the same sentence as 5 diseases in open-access papers, as found by Europe PMC text mining. Sharing a sentence is not in itself a finding about the gene and the disease. The quoted sentences say what the papers report.
gastric tumors (1 paper, 2025). "Studies on gastric tumors have suggested potential roles for snoRNAs such as SNORA42, SNORA74A, and SNORD10 in gastric tumor pathogenesis." (PMID 40584410, 2025). "Studies on gastric tumors have suggested SNORA42, SNORA74A, and SNORD10 require further investigation to ascertain their potential as therapeutic targets." (PMID 40584410, 2025).
tumor (1 paper, 2025). "On days 14 and 21 post‐injection, we observed an obvious reduction in liver tumor incidence and tumor size in Snora74a KO mice compared to WT littermates." (PMID 40270470, 2025). "We observed that DAPT treatment dramatically inhibited tumor formation and tumor growth, and consequently improved survival rates of Snora74a KO and WT mice with bearing tumors." (PMID 40270470, 2025). "Liver‐to‐body weight ratios, key indicators of tumor malignancy, were also significantly reduced in Snora74a KO mice compared to WT mice." (PMID 40270470, 2025). "Overall, SNORA74A drives the self‐renewal of liver CSCs and Snora74a knockout abrogates tumor development and propagation." (PMID 40270470, 2025). "Next, we determined the role of Snora74a in HCC development using a tumor induction mouse model." (PMID 40270470, 2025).
SNORA74A also shares sentences with these, for which no sentence is quoted: cancer (2 papers); gastric cancer (1); leukemia (1).